EIF4E (eukaryotic translation initiation factor 4E)
Diseases named in the same sentence as EIF4E in open-access papers (continued):
Sharing a sentence is not in itself a finding about the gene and the disease.
breast carcinoma (continued). "This study was undertaken to evaluate the effects of RRs on growth inhibition, MAPK/Mnk mediated eIF4E protein translational machinery and downstream biological effects in triple negative and Her2 overexpressing breast cancer cells." (PMID 24504069, 2014). "Increased levels of eIF4E and activated translation initiation are also considered crucial for breast cancer progression and angiogenesis." (PMID 24504069, 2014). "Depletion of RPL24 in breast cancer cells by >70% reduced cell viability by 80% and decreased protein expression of the eIF4E-dependently translated proteins cyclin D1 (75%), survivin (46%) and NBS1 (30%) without altering GAPDH or beta-tubulin levels." (PMID 24970821, 2014). "eIF4E is also identified as a poor prognostic marker in several breast cancer retrospective and prospective studies." (PMID 24504069, 2014). "Recent reports have indicated Mnk-mediated eIF4E phosphorylation on serine 209 to be chiefly responsible for cellular transformation in many tumors including that of breast cancers." (PMID 24504069, 2014). "In this study, we have identified potential therapeutic agents that prevent Mnk-dependent phosphorylation of eIF4E in different breast cancer cell subtypes including TNBC for which targeted therapies are currently not available." (PMID 24504069, 2014). "Several studies in recent years have identified the oncoprotein eIF4E and its phosphorylated forms to be overexpressed in breast carcinomas." (PMID 24504069, 2014). "Eukaryotic translation initiation factor 4E (eIF4E1) along with EGFR have been identified as proteins expressed in brain metastatic cells originating from breast cancer." (PMID 24244833, 2013). "As a proof of concept, in previous work we have shown that eIF4E siRNA knockdown inhibits cancer cell growth in a variety of breast cancer cell subtypes." (PMID 23102376, 2012). "eIF4E is overexpressed in breast cancer and has been suggested to be an indicator of poor prognosis." (PMID 23102376, 2012). "In the context of clinical breast cancers, we estimated eIF4E activity by analysing expression of eIF4E and its functional regulators within tumour cells and combining these scores to reflect inhibitory and activating influences on eIF4E." (PMID 21320304, 2011). "Pathways activated in breast cancer include Eukaryotic Translation Initiation Factor 4E (eIF4E) pathway, Phosphatidylinositol-3-kinase(PI3K)-AKT pathway, Mitogen-Activated Protein Kinase (MAPK) pathway and the Nuclear factor-kappaB (NFkB) pathway." (PMID 19134194, 2009). "In the current study, we have analyzed the expression of eIF4E along with 5 of its downstream effector proteins in human breast carcinoma specimens using immunohistochemical analysis of TMAs." (PMID 19134194, 2009). "In conclusion, eIF4E preferentially upregulates gene products that are involved in worse clinical outcome in breast cancer, head and neck cancer, and others." (PMID 19134194, 2009). "In common with initial publications on eIF4E's role in cancer and much of the subsequent literature, we have focused on breast cancer." (PMID 19367274, 2009). "For instance, eIF4E levels are elevated, at least in part, in breast cancer and head and neck squamous cell carcinomas due to amplification of the eIF4E gene." (PMID 20049173, 2009). "Decreasing levels of eIF4E in the human breast cancer cell line MDA-MB-435 and human prostate cancer cell line PC-3 diminished their angiogenic and tumorogenic properties." (PMID 20049173, 2009). "Eukaryotic initiation factor 4E (eIF4E) is elevated in many cancers and is a prognostic indicator in breast cancer." (PMID 19134194, 2009). "Breast cancer patients with high eIF4E expression (>7-fold to normal) experienced a statistically significant poorer clinical outcome with a higher risk for recurrence and cancer related death." (PMID 20049173, 2009). "This same strategy, combining siRNA to eIF4E with cis-platin, was also used in breast carcinoma cells with success." (PMID 20049173, 2009).
breast carcinoma (continued). "It has been demonstrated that eIF4E overexpression is associated with eIF4E gene amplification in both HNSCC and in breast carcinomas." (PMID 20049173, 2009). "eIF4E overexpression was detected at a range of 3–30 fold in breast carcinomas, compared to normal breast tissue, and eIF4E levels were significantly increased in vascularized malignant ductules of invasive carcinomas." (PMID 20049173, 2009). "Another miRNA whose binding sites are underrepresented on eIF4E responsive mRNAs is miR-27b that is often decreased in breast cancer tissues and functions as a negative regulator of CYP1B1, a protein whose genotype correlates with prostate cancer risk." (PMID 19290046, 2009). "In the present study, we have examined this possibility as well as furthered the investigation into eIF4E's relationship to angiogenesis, by testing biopsies from a large sample of patients with untreated breast cancer." (PMID 17010208, 2006). "Here we have shown that eIF4E, as revealed by immunohistochemistry, is overexpressed in breast cancer tissue." (PMID 17010208, 2006). "The role of eIF4E as a viable target to block the development of angiogenesis and advanced breast cancer deserves further investigation." (PMID 17010208, 2006). "The overexpression of eukaryotic translation initiation factor 4E (eIF4E), a key regulator of protein synthesis, is involved in the malignant progression of human breast cancer." (PMID 17010208, 2006). "In breast carcinoma, localization of eIF4E protein overexpression was mainly cytoplasmic in the cancer cells, but not in the adjacent normal-looking ductal epithelial cells and stromal elements." (PMID 17010208, 2006). "This study investigates the relationship between eIF4E and angiogenesis, as well as their prognostic impact in patients with human breast cancer." (PMID 17010208, 2006). "For example, the overexpression of EIF4E as well as EIF4G1 has been shown to transform normal cells and increased expression of EIF4E has been found in breast cancer cell lines." (PMID 14997205, 2004). "Targeting EIF4E‐related pathways could provide new therapeutic strategies to improve breast cancer patient outcomes." (PMID 40842081, 2025). "The role of eIF4E as a key player in oncogenic transformation is supported by previous studies; phosphorylation of eIF4E occurs in breast cancer cells following exposure to growth factors and chemotherapy while its de-activation inhibited proliferation of lung and prostate cancer cells." (PMID 37888706, 2023). "Since eIF4E phosphorylation is mainly mediated by MNK2 in breast cancer cells MDA-MB-231, this could also occur in lung cancer cells." (PMID 37111758, 2023). "The result suggested that increased expression of eIF4E may be a vital factor for development of breast cancer." (PMID 36387239, 2022). "Likewise, in vitro studies reported that breast cancer cell migratory activity and invasiveness were significantly attenuated when eIF4E was knocked out." (PMID 36360287, 2022). "Since mTORC1 regulates eIF4E abundance through 4EBP1 phosphorylation, thus, there exist an intriguing possibility of a positive feedback interaction between polyamines and mTOR pathway in regulating breast cancer cells growth." (PMID 36135836, 2022). "Similarly, lncRNA RP1-5O6.5 has been shown to interact with eIF4E and prevents binding of eIF4E to eIF4G, leading to inhibition of translation of p27kip1, which negatively regulates Snail levels in breast cancer cells." (PMID 33672592, 2021). "Elevated eIF4E expression was found to correlate with worse overall and disease-free patient survival, which confirmed eIF4E level to be an independent prognostic factor for breast cancer." (PMID 34344911, 2021). "Moreover, while upstream components of the MAPK and PI3K pathways often show a heterogeneous expression pattern in tumors, the expression of phospho-eIF4E and phospho-4E-BP are more diffuse within the tumor and are overexpressed in breast cancer." (PMID 32517051, 2020).
breast carcinoma (continued). "In the present study, eIF4E was down-regulated by Rab7a knockdown, suggesting that Rab7a might promote breast cancer through regulating eIF4E." (PMID 29769411, 2019). "Moreover, a strong relationship between MNK-mediated phosphorylation of eIF4E has been demonstrated in prostate and breast cancers." (PMID 31756179, 2019). "mTOR/eIF4E axis is found to contribute to breast cancer maintenance and progression." (PMID 29769411, 2019). "To further determine whether the activation of Wnt/β-catenin in breast cancer cells is eIF4E-dependent, we depleted eIF4E using two independent siRNAs in breast cancer cells and examined β-catenin activities in these cells exposed to chemotherapeutic drugs." (PMID 27926520, 2017). "In addition, CGP57380 or cercosporamide prevented the chemo drugs-induced eIF4E-mediated β-catenin increase in breast cancer cells." (PMID 27926520, 2017). "Given that Wnt/β-catenin signalling activation is the consequence of eIF4E phosphorylation in breast cancer cells and chemotherapy increases eIF4E phosphorylation, we next investigated whether chemotherapy induces the activation of Wnt/β-catenin signaling." (PMID 27926520, 2017). "We observed that eIF4E phosphorylation at S209 is a consistent feature in advanced breast cancer patients and in all tested breast cancer cell lines, including an ERα-positive line and HER2-, ERα- and PR-negative lines, which affects the response to chemotherapy." (PMID 27926520, 2017). "In addition, eIF4E knockdown reportedly decreases the breast cancer cell proliferation, and inhibition of MNK kinase activity by cercosporamide or CGP57380 effectively targets lung, prostate and breast cancer cells." (PMID 27926520, 2017). "However, MNK inhibitors prevented chemotherapeutic drug-induced eIF4E phosphorylation and β-catenin activation, which enhanced the breast cancer cell response to chemotherapy in vitro and in vivo." (PMID 27926520, 2017). "However, chemotherapeutic drugs at the same concentration inhibited ~90% of proliferation and induced 85% of apoptosis in eIF4E-depleted breast cancer cells." (PMID 27926520, 2017). "eIF4E overexpression is further regarded as a poor prognostic marker for breast cancer." (PMID 24504069, 2014). "The significantly abnormal over-expression of p-eIF4E protein is found in a number of tumors including non-small cell lung cancer, breast cancer, gastric cancer, colon cancer, prostate cancer, penile squamous cell carcinoma, head and neck cancer and primary central nervous system lymphoma." (PMID 24551240, 2014). "The ability of the RRs to induce Mnk degradation and block eIF4E phosphorylation may further block the eIF4E mediated cap dependent translation in breast cancer cells." (PMID 24504069, 2014). "Recent findings suggest that overexpression of eukaryotic translation initiation factor 4E (eIF4E) in breast cancers critically augments CAP-dependent mRNA translation and synthesis of proteins involved in cell growth, cell proliferation, invasion and apoptosis evasion." (PMID 24504069, 2014). "Given the known role of RPL24 in murine tumorigenesis and therapeutic interest in eIF4E-driven human breast cancers, we asked if RPL24 expression is also altered during human breast tumorigenesis, and observed that most human breast cancers overexpress RPL24 relative to normal breast tissue." (PMID 24970821, 2014). "Thus, targeting Mnk/eIF4E pathway that is critical for cancer cell growth, survival and tumor progression is an ideal and attractive strategy for therapeutic intervention of breast cancers." (PMID 24504069, 2014). "It has been shown that eIF4E is an independent prognostic factor in breast cancer." (PMID 19134194, 2009). "In addition, some studies have found increased eIF4E expression during hypoxic conditions by IHC analysis of confined breast cancer biopsies." (PMID 20049173, 2009). "Our research has focused on the role of the eIF4E in human breast cancer." (PMID 19134194, 2009).
breast carcinoma (continued). "Indeed, eIF4E is elevated in numerous types of cancers, including bronchioalveolar, bladder, head and neck, liver, colon, and breast cancers." (PMID 16404421, 2006). "Based on the previous observation and our results, we hypothesize that eIF4E overexpression is likely more important than nodal status in predicting breast cancer recurrence and outcome." (PMID 17010208, 2006). "Specifically, our findings show that eIF4E may be an important regulator of production of angiogenic factors, such as IL-8 and VEGF that are associated with poor prognosis in breast cancer." (PMID 17010208, 2006). "Also, a nonphosphorylatable mutant of 4E-BP1, which constitutively binds eIF4E, inhibits breast cancer cell growth more strongly than wild-type 4E-BP1." (PMID 16404421, 2006). "In the context of HER2‐negative breast cancer, EIF4E may be a viable therapeutic target." (PMID 40842081, 2025). "We hypothesise that elevated EIF4E levels promote HER2‐negative breast cancer cell proliferation, migration and invasion by regulating molecules associated with Wnt signalling and ECM components, thereby contributing to disease progression and poorer patient outcomes." (PMID 40842081, 2025). "Therefore, RNAi driven by Survivin promoter targeting eIF4E could be used as an adjuvant therapy tool for human breast cancer, with tumor specificity and efficiency." (PMID 37601696, 2023). "Notably, transcriptome and proteome analyses using data from The Cancer Genome Atlas (TCGA) and Clinical Proteomic Tumor Analysis Consortium (CPTAC) have revealed consistent upregulation of MNK1/2 and eIF4E in most breast cancer cases at mRNA and protein level except MNK1 mRNA." (PMID 37766871, 2023). "Western blot confirmed high eIF4E expression was consistently found in resistant cell lines, suggesting that overexpression of eIF4E might contribute to tamoxifen resistance in breast cancer." (PMID 32066877, 2020). "Mnk2-mediated hyperactivation of eIF4E may promote the growth and survival of breast cancer." (PMID 32106418, 2020). "Also, the MYC/eIF4E axis is a mediator of drug resistance to BEZ-235 in breast cancer cells." (PMID 32409685, 2020). "The present study therefore authenticates a novel function for RRs in degrading Mnk and blocking eIF4E dependent translational initiation, and further endorses the notion that RRs are novel potential therapeutic agents for treating triple negative and Her2 overexpressing breast cancers." (PMID 24504069, 2014). "Here, we take a different approach and estimate the activity of eIF4E, one of the key effectors of mTORC1 function, and investigate whether this reflects response to mTOR inhibition in both tissue culture and in clinical breast cancers." (PMID 21320304, 2011). "Thus, it appeared that there might be significant relationships between the overexpression of eIF4E, angiogenesis, cancer recurrence, and patient survival in breast cancer." (PMID 17010208, 2006). "In the present study, we examine the level of expression of eIF4E in order to analyze any correlations with the molecules initiating angiogenic pathways and patient prognosis, using histological samples from a relatively large number of patients with previously untreated breast cancer." (PMID 17010208, 2006). "We highlight m7G regulatory gene potential, particularly EIF4E, as prognostic markers and therapeutic targets for HER2‐negative breast cancer." (PMID 40842081, 2025). "The results showed that the expression levels of AGO2 and EIF4E3 were significantly lower in breast cancer cell lines than in the normal breast cell line, whereas the expression levels of DCPS and EIF4E were significantly higher." (PMID 37353728, 2023).